PCSK9 (proprotein convertase subtilisin/kexin type 9)
Diseases named in the same sentence as PCSK9 in open-access papers (continued):
Sharing a sentence is not in itself a finding about the gene and the disease.
psoriasis (continued). "Based on its efficacy, safety profile, and negligible adverse effects, PCSK9 could be a new option in the treatment of psoriasis in combination with lipid metabolic disorders." (PMID 36035406, 2022). "Therefore, further investigations on the exact role of PCSK9 in psoriasis and its comorbidities are needed." (PMID 32456228, 2020). "Additionally, the authors also investigated PCSK9 levels in lesions of psoriasis patients using quantitative RT-PCR assays, which have shown that PCSK9 expression was five times higher in psoriatic plaques compared to unaffected skin." (PMID 32456228, 2020). "Other than the research cited above, the data linking PCSK9 to psoriasis are still limited." (PMID 32225075, 2020). "It suggests that elevated PCSK9 levels are involved in lipid metabolism in psoriasis but are not directly linked to variations in LDL levels." (PMID 32225075, 2020). "Furthermore, we aimed to measure the clinical significance of PCSK9 in psoriasis and its potential importance in estimating the probability of cardiometabolic events in patients with psoriasis with highlighted regard to proatherogenic lipid profile." (PMID 32225075, 2020). "Further, we speculate that measuring PCSK9 levels could be useful in choosing the best psoriasis therapy method." (PMID 32225075, 2020). "We proved that PCSK9 levels cannot be used as a marker of effectiveness of psoriasis treatment." (PMID 32225075, 2020). "Furthermore, NAFLD, closely related to psoriasis, increases circulating PCSK9 concentrations independently of metabolic modifiers." (PMID 32225075, 2020). "More importantly, PCSK9 associated with psoriasis appears to be independent of cholesterol metabolism." (PMID 33364976, 2020). "PCSK9 has been recognized in the last years as the molecule that may be directly involved in the occurrence and progression of psoriasis." (PMID 32456228, 2020). "Another link between PCSK9 and psoriasis may be mediated by adiponectin receptor agonists (AdipoR agonists) activation." (PMID 32456228, 2020). "Moreover, our recent studies reported that metabolic-associated genes PCSK9 and nuclear receptor interacting protein 1 (NRIP1) both play important roles in psoriasis via the NFκB pathway." (PMID 31824416, 2019). "Concerning the role of resistin in psoriasis, in addition to its effect on proinflammatory cytokine production, its connection with proprotein convertase subtilisin/kexin 9 (PCSK9) may represent another key mechanism." (PMID 31824416, 2019). "According to their research, targeting PCSK9 may be a promising therapeutic for psoriasis." (PMID 37234169, 2023). "Indeed, plasma PCSK9 concentration is increased in patients with psoriasis." (PMID 33364976, 2020). "The analysed protein PCSK9 has multidirectional activity towards many organs and significantly augments theirs functions, which could entail a revaluation of its factual function in psoriasis." (PMID 32225075, 2020). "Moreover, PCSK9 affects the cell cycle and apoptosis of keratinocytes and may become a target in the context of psoriasis in the future." (PMID 33364976, 2020). "As a result, resistin may act as an activator of PCSK9 in the pathogenesis of psoriasis." (PMID 31824416, 2019). "Importantly, together, PCSK9 and NRIP1 may be two potential therapeutic targets for both psoriasis and metabolic syndrome by regulating the NFκB-associated chronic inflammatory status." (PMID 31824416, 2019). "The extension of the study group in the future should allow for the analysis of the correlation between PCSK9 or NGAL and psoriasis with difficult-to-treat areas (anogenital, nails, hands and feet, scalp involvement)." (PMID 37763277, 2023). "Induction of PCSK9 was observed in the lesional skin of both psoriatic patients and IMQ-induced psoriasis mouse model." (PMID 35075118, 2022). "One study showed that 3 months of methotrexate monotherapy reduced PCSK9 levels and improved psoriasis, indicating that PSCK9 could be used as a marker of psoriasis activity." (PMID 39736777, 2024).
psoriasis (continued). "Furthermore, they postulated that PCSK9 is connected with a higher atherosclerotic burden in psoriasis patients, and, using blood transcript analysis, they identified TNF, IL6, IL17A, and IL23 as PCSK9-related pathways." (PMID 37234169, 2023). "Furthermore, several proteins, such as KRT17, KRT17, TWEAK, PCSK9, and ANGPTL4, are highly expressed in psoriasis and tumors and are involved in the development of these two diseases, and knockdown of these proteins exhibits therapeutic effects." (PMID 37762693, 2023). "PCSK9 did not correlate with psoriasis activity expressed by the PASI score in the patient’s group before treatment." (PMID 32225075, 2020). "According to these and our own results, we assume that PCSK9 is a novel biomarker of psoriasis, but not of its severity." (PMID 32225075, 2020). "One study found increased PCSK9 levels in psoriasis patients, irrespective of disease severity." (PMID 38185721, 2024). "The change of NGAL and PCSK9 after cyclosporine therapy has not yet been investigated in psoriasis." (PMID 37763277, 2023). "Nevertheless, there are no clinical studies on the effect of PCSK9 on psoriasis." (PMID 36035406, 2022). "We first parsed 2 RNA-Seq data sets — a newly generated data set derived from primary human keratinocytes isolated from healthy individuals without psoriasis and a data set derived from nonlesional skin that we previously generated — to characterize the effect of SNP rs662145 on PCSK9 expression." (PMID 35862195, 2022). "There is no more related data concerning psoriasis and PCSK9." (PMID 32225075, 2020).
liver disease (23 papers, 2017 to 2026). "Collectively, there are a variety of causes of liver disease, and it is likely that PCSK9 expression correlates with certain forms of the disease (i.e., diet-induced liver disease)." (PMID 35323658, 2022). "In multivariable models, race, cause of ARDS, body mass index, pre-existing liver disease, body temperature, sodium, white blood cell count and platelet count were associated with PCSK9 level." (PMID 35770004, 2022). "This suggests that associations of PCSK9 with residual liver function are affected by liver disease severity and disease etiology." (PMID 33920491, 2021). "Purpose of this study was to find associations of plasma PCSK9 with circulating cholesterol and sphingolipid species and measures of liver disease severity in patients with liver cirrhosis." (PMID 33461570, 2021). "In addition, PCSK9 influences metabolic dysfunction–associated steatotic liver disease, with its hepatic expression levels correlating with disease severity and affecting bariatric surgery outcomes." (PMID 40764605, 2025). "All of these liver diseases are associated with increased serum PCSK9 levels." (PMID 41271978, 2025). "In summary, liver diseases can have diverse triggers, and PCSK9 expression may be associated with specific types of liver diseases, for example, NAFLD/NASH and HCV." (PMID 38185721, 2024). "Additionally, PCSK9 is associated with many human diseases such as liver disease, kidney disease, and diabetes." (PMID 36655117, 2023). "An alternative explanation for decreased levels of PCSK9 in association with advanced liver disease could be an accumulation of bile acids in the liver." (PMID 28727814, 2017). "By lowering LDL cholesterol levels and modulating vascular dynamics, PCSK9 inhibitors alleviate hemodynamic disturbances in portal hypertension, potentially enhancing liver circulation and reducing intrahepatic vascular resistance." (PMID 39997697, 2025). "In our cohort, modest correlations were mostly observed between PCSK9 levels and markers of liver disease in patients with IBD of both sexes." (PMID 40265438, 2025). "PCSK9 plays multifaceted pathological roles in hepatocytes, affecting cholesterol metabolism, liver diseases, and cancer." (PMID 40764605, 2025). "Collectively, these studies underscore the complex and multifaceted roles of PCSK9 in hepatic pathophysiology, extending beyond its traditional role in cholesterol regulation to encompass broader implications in liver disease and cancer progression." (PMID 40764605, 2025). "By focusing on randomized controlled trials and incorporating PCSK9 inhibitors into the therapeutic arsenal for portal hypertension, we can move closer to an evidence-based approach for improving outcomes in these challenging patients." (PMID 39997697, 2025). "For this reason, as well as others, PCSK9 has now been shown to regulate hepatic lipid content and potentially affect the onset and progression of liver disease." (PMID 35323658, 2022). "Both the secreted and intracellular forms of PCSK9 have been shown to play a role in a variety of diseases such as liver disease, CKD, neurodegenerative disease." (PMID 35323658, 2022). "It remains to be determined if serum PCSK9 concentrations decline over time during chronic liver injury to reach lowest levels at end-stage liver disease." (PMID 35162992, 2022). "Bacteremia patients with liver diseases also had low plasma PCSK9 levels in comparison to bacteremia patients with normal liver function." (PMID 35162992, 2022). "It is also likely that PCSK9 expression correlates with liver disease only during certain stages of the disease." (PMID 35323658, 2022). "Median PCSK9 was 148 ng/mL in our patient cohort and 106 ng/mL in the cohort with very severe liver diseases." (PMID 33461570, 2021). "In cirrhotic patients, the impact of liver disease seems to override the effect of viral eradication on serum PCSK9." (PMID 33920491, 2021).
liver disease (continued). "The present examinations indicate that the negative association between the hepatic LDL-receptor protein levels and PCSK9 was lost in patients with severe liver diseases." (PMID 33461570, 2021). "The mean PCSK9 levels in the study population were much lower than those found in normal or healthy populations, with PCSK9 levels of healthy populations more than double the mean level of those with liver disease in the present study." (PMID 28727814, 2017). "Further studies with more patients are needed to unravel a possible independent role of PCSK9 on mortality in end-stage-liver disease patients." (PMID 28727814, 2017). "Furthermore, this review explores the pleiotropic effects of PCSK9 beyond lipid metabolism, and comments on its potential application value and latest research advances in diseases such as infection, liver disease, and malignancy." (PMID 42256395, 2026). "PCSK9 is highly abundant in the liver, and patients with liver disease may have elevated serum levels." (PMID 40265438, 2025). "Moreover, the dysregulation of SREBP-2 and PCSK9 has been reported in cases of liver disease, such as hepatitis, suggesting the involvement of both proteins." (PMID 41233786, 2025). "Although some studies imply that PCSK9-iTs could be beneficial in treating hepatic disorders such as steatosis, caution should be exercised when prescribing PCSK9-iTs for patients with HCV infection." (PMID 38185721, 2024). "PCSK9 expression may also correlate with liver diseases at specific stages and may function in different ways." (PMID 38185721, 2024). "Future efforts should focus on developing safer, novel, and precision therapeutic strategies to target PCSK9, either independently or in conjunction with existing therapies for the treatment of CVDs, liver diseases, infections, autoimmune disorders, neurocognitive disorders, cancers, and etc." (PMID 38185721, 2024). "Regulation of PCSK9 activity can impact patients with liver disease such as hepatic steatosis." (PMID 36655117, 2023). "Thus, further research in larger populations must resolve the complex interplay between PCSK9 levels in serum, hepatic synthesis, liver disease severity and disease etiology." (PMID 33920491, 2021). "Thus, while preliminary data on PCSK9 inhibitors are promising, rigorous clinical trials are essential to determine their role in the management of portal hypertension and their potential as adjunctive therapies in the treatment of liver diseases." (PMID 39997697, 2025). "LPS induced hepatic PCSK9 but whether intestinal PCSK9 production was affected by LPS or was associated with liver disease severity was not evaluated in that study." (PMID 33461570, 2021). "Serum PCSK9 negatively correlated with the model for end-stage liver disease (MELD) score, which is the state-of-the-art scoring model of liver disease severity." (PMID 33920491, 2021). "Serum PCSK9 levels did mostly not correlate with serum cholesterol, markers of liver disease severity, the model for end stage liver disease score, or fibrosis stage." (PMID 41271978, 2025). "However, our cohorts were small, so this study is not suitable for drawing final conclusions about the effect of statins on hepatic PCSK9 or SREBP-2, or on the prevalence of metabolic and liver diseases." (PMID 41233786, 2025). "This comprehensive review delineates the intricate roles and wide-ranging implications of PCSK9, extending beyond CVD to emphasize its significance in diverse physiological and pathological states, including liver diseases, infectious diseases, autoimmune disorders, and notably, cancer." (PMID 38185721, 2024). "It is also unclear if the etiology of liver disease in this cohort (HBV, n = 14; HCV, n = 15; ethanol abuse; n = 3; non-alcoholic steatohepatitis (NASH), n = 4; other etiologies, n = 3) impacts hepatic PCSK9 expression, secretion and/or PCSK9 circulation." (PMID 35162992, 2022).
liver disease (continued). "Our study identified elevated PCSK9 levels in serum of patients with chronic HCV compared to non-infected patients without severe liver diseases." (PMID 33920491, 2021). "Comparison of hepatic PCSK9 protein in patients with viral and non-viral related liver diseases showed that PCSK9 protein was strongly induced in HCV liver." (PMID 33461570, 2021). "Liver diseases connected to FASN can thus be treated (by silencing PKLR, PCSK9 or PNPLA3) without experiencing the side effects associated with direct FASN inhibition." (PMID 28827398, 2017). "This is based on the comparable expression of PCSK9 and SREBP2 protein levels in the hepatocytes from severely ill patients with and without SARS-CoV-2 infection, as well as similar liver histology and levels of systemic markers of liver disease in cases and controls." (PMID 41233786, 2025). "Humans with genetic inhibition of PCSK9 are not at an increased risk of developing MASLD19, and the association of PCSK9 with liver disease in patients with common causes of liver injury remains unclear." (PMID 41271978, 2025). "This suggests that higher serum PCSK9 levels are not specific to rare liver diseases." (PMID 41271978, 2025). "Although PCSK9 inhibitors have not yet been extensively studied in the context of portal hypertension, their effects on improving lipid metabolism may suggest their potential benefits in treating this condition." (PMID 39997697, 2025). "The rather expensive PCSK9 therapy is not recommended in normolipidemic patients, and its impact on liver disease is still unknown." (PMID 35162992, 2022). "Future research with larger patient cohorts may be able to determine if PCSK9 levels are impacted by different etiologies of liver disease rather than progression of fibrosis." (PMID 35162992, 2022). "Similarly, PCSK9 protein did not change with increasing liver disease severity in patients with NAFLD." (PMID 33461570, 2021). "Having shown that plasma PCSK9 did not decline with measures of liver disease severity it was suggested that hepatic PCSK9 expression may also be unaffected." (PMID 33461570, 2021). "In addition, we found a negative correlation between MELD, a score for liver disease, and PCSK9." (PMID 32998342, 2020). "Correlations of PCSK9 and the MELD score could not be observed in non-HCV-infected patients with severe liver diseases." (PMID 33920491, 2021). "Therefore, the animal study using PCSK9-null mice (particully on an nonoptimal background for studies of liver inflammation and injury) may not be relevant clinically, and PCSK9 inhibitor could be considered as a safe pharmacological therapeutic for liver diseases." (PMID 31748600, 2019).